CXCL9 (C-X-C motif chemokine ligand 9)
Diseases named in the same sentence as CXCL9 in open-access papers (continued):
Sharing a sentence is not in itself a finding about the gene and the disease.
tumor (continued). "IL-17 was reported to inhibit T cell attracting chemokines CXCL9 and CXCL10, thereby inhibiting the recruitment of CD8+ T cells and Treg cells in CRC, which helped the immune escape of tumor cells." (PMID 35865173, 2022). "Some of these biomarkers are immunosuppressive or have pro-tumor activity such as PD-L1, IL17RE, LAG-3, IDO-1, TIM-3 whereas others have antitumor activity such as CD8+ T-cells, OX40, CXCL9 and others have a mixed role such as IFN-G." (PMID 36612271, 2022). "CXCL9 is abundantly expressed in several solid tumors, including CM, and it stimulates the infiltration of CD4+T and CD8+T lymphocytes into tumor cell regions, hence boosting the response of cytotoxic T lymphocytes and destroying tumor cells." (PMID 35957907, 2022). "CXCL9 can bind to CXCR3 expressed in tumor cells to recruit CD4 + T cells, thus promoting the production of CCL5 in TME, promoting tumor invasion." (PMID 36159780, 2022). "CXCL9, CXCL10, and CXCL11 bind to CXCR3 and regulate lymphocyte chemotaxis to mediate recruitment of tumor-infiltrating lymphocytes (TIL) for tumor-suppressor activity." (PMID 35269786, 2022). "M1-Mφs function as inhibiting tumor progression by secreting pro-inflammatory cytokines (IFN-α/β/γ and IL-12) and chemokines (CXCL9 and CXCL10), which can attract CTL and NK cell to restrict tumor growth." (PMID 35155237, 2022). "Among these chemokines, the tumor cell-derived chemokines CXCL9 and CXCL10 are critical in attracting CD8+ T lymphocytes to tumor tissues." (PMID 36284313, 2022). "CXCL9 and CXCL10 can effectively inhibit angiogenesis, enhance apoptosis and immune infiltration of tumor cells, and enhance antitumor immunity in platinum-based chemotherapy drug treatment." (PMID 36590751, 2022). "The presence of myeloid-cell-derived CXCL9 and CXCL10 in the tumor microenvironment can predict response to immunotherapy." (PMID 35626062, 2022). "Differentially expressed cytokines (CCL5, CCL19, CXCL9 and CXCL10) were related to the overall survival, and their expression levels were also examined both in tumor tissues of CL-BCa patients by IHC and in typical CL-BCa cell lines by qPCR." (PMID 35359417, 2022). "CXCR3 is a CXC chemokine receptor dominated by IFN-γ, which interacts with CXCL9, CXCL10, and CXCL11 to regulate tumor progression and cytokine secretion." (PMID 35571062, 2022). "The expression levels of other hub genes CTLA4, CXCL10, CCL5, CCl4, ICAM1, CXCL9, CD27, GZMB, FCGR2A, SELL, IDO1 in SKCM were higher than those in non-tumor skin tissues (P < 0.05), and the results were statistically significant." (PMID 35710862, 2022). "CD4+ T cell IFN-γ-inducible chemokines CXCL9, CXCL10, and CXCL11 recruit effector T cells to the TME, direct tumor infiltration, and are key players in T cell homing." (PMID 34012451, 2021). "During inflammation, tumor infiltrating immune cells produce INF-γ, which in turn activates a variety of INF-γ-induced genes through the JAK/STAT pathway, such as CXCL9, CXCL10 and CXCL11." (PMID 34200459, 2021). "Our results showed that the expression of CXCL9, CXCL10, and CXCL11 was significantly higher in tumor than in adjacent normal tissues in 136 CRC patients." (PMID 34539647, 2021). "The refined six gene tumor immune signature (IDO1, CXCL10, CXCL9, HLA-DRA, STAT1, IFNG) was carried on a sample of cases representative of the Sema4D HIS subtypes using basic nSolver analysis." (PMID 33776991, 2021). "CTTCs including CXCL9, CXCL10, CXCL11, and CCL5, which were differentially expressed between tumor and adjacent normal tissues, were significantly correlated with the abundance of several OTUs." (PMID 34539647, 2021). "We found that whole-tumor gene expression of T cell marker factors (CD8 and IFN-γ) and chemokines (CXCL9 and CXCL10) were significantly enhanced after ICT treatment, while inflammatory factors (IL6, IL10 and TNF-α) were reduced." (PMID 33460401, 2021).
tumor (continued). "This set includes tumor expression of c-Met and serum levels of HGF, IL-6, IL-8, CXCL9, CXCL10 and CXCL11." (PMID 34200459, 2021). "When tumor cells produce EMT, they often secrete more cytokines such as CXCL9 and CXCL10, which can inhibit the function of NK cells, thus promoting tumor immune escape." (PMID 33992097, 2021). "It is somehow puzzling that cancer cells also produce CXCL9 and CXCL10 and that this correlates with a better prognosis, in part due to the induction of anti-tumor CD4+ and CD8+ T cells." (PMID 34944943, 2021). "It is therefore likely that the increased expression of CXCR3 seen on the T cells in draining lymph node in vivo is in response to paracrine CXCL9 and CXCL10 signals possibly from the tumor." (PMID 34336705, 2021). "IFN-induced STAT1 can subsequently activate chemokines, such as CXCL9, CXCL10, and CXCL11, which can recruit more CD8+ T cells to provide anti-tumor immunity." (PMID 34282238, 2021). "In an independent study, macrophage-derived CXCL9 and CXCL10 were significantly elevated in response to immune checkpoint inhibition and were required to mount effective CTL-driven anti-tumor immune responses." (PMID 33807608, 2021). "Inhibition of EZH2 and DNMT1 by chemical inhibitors restored the expression of CXCL9 and CXCL10 and increased effector T cell tumor infiltration." (PMID 34262562, 2021). "Our data indicate, however, that antibody-treated mice did show reduced CXCL9, CXCL10, and CCL5 chemokine production within the tumour mass, and a corresponding reduction in the number of tumour-infiltrating T cells." (PMID 33925140, 2021). "CXCL9/10/11 exerted their biological effects related to EMT via CXCR3, which was upregulated in the invasive front of the CRC tumor tissues." (PMID 34233297, 2021). "The CRC patients were then categorized into two groups according to the expression level of CTTCs (CXCL9, CXCL10, CXCL11, and CCL5) in tumor." (PMID 34539647, 2021). "CXCL9 is a critical chemokine that binds CXCR3 on T cells, enhancing recruitment of cytotoxic CD8+ T cells into the tumor and promoting the differentiation of inflammatory T helper type 1 (Th1) and Th17 CD4 T cells." (PMID 33508232, 2021). "CXCL9 and CXCL10 are the major Th1 chemokines responsible for T cell recruitment to the tumor microenvironment." (PMID 33403469, 2021). "Collectively, the results indicated that the three CTTCs (CXCL9, CXCL11, and CCL5) were selectively regulated in tumor or adjacent normal tissues and decreased with progressive stages in CRC patients." (PMID 34539647, 2021). "The increased expression of six CXC chemokines (CXCL4, CXCL9, CXCL10, CXCL11, CXCL12, and CXCL13) was related to tumor progression." (PMID 33767987, 2021). "On the other hand, rich expression of IFN-γ, CXCL9, and CXCL10 and significantly high CTLA-4 or PD-1+ CD8/CD4 T cells were observed in the tumor microenvironment of CMS 1 patients." (PMID 33968712, 2021). "CAFs-3 from the primary tumor showed distinct expression of other chemokines and growth factors, such as C3, CCL5, IGF1, CXCL10, CXCL9, and CXCL14, in addition to CCL19 and IGF2." (PMID 34790166, 2021). "CCL18+M1, CXCL9+M2, and TIMP1+M3 were enriched in tumor tissues and were regarded as TAMs, whereas SELENOP+M4, MMP7+M5, CHIT1+M6, and PPARG+M7 were enriched in normal tissues and considered as resident tissue macrophages (RTMs)." (PMID 34659209, 2021). "Simultaneously, CXCL9 and CXCL10 have been shown to increase levels of tumor infiltrating CD8+ effector T cells and NK cells, minimize metastasis, and are correlated with improved responses to checkpoint blockade and adoptive cell transfer therapies." (PMID 34012451, 2021). "Dendritic cells play critical roles in antigen presentation, cross-priming and activation of cytotoxic T cells, and produce CXCL9 and CXCL10 to recruit tumor-specific T cells to the tumor sites." (PMID 34579759, 2021).
tumor (continued). "It was well known that CD8+ T cells and NK cells can be recruited via the CXCL9–11/CXCR3 axis, resulting in tumor-suppressing with a form of paracrine." (PMID 34321012, 2021). "Combination therapy using cisplatin and cGAMP enhances the gene expression of CXCL9 and CXCL10 in tumor tissues and inhibits tumor growth." (PMID 34830754, 2021). "Some of these changes are beneficial when it comes to non-tumor-promoting conditions, e.g., the decrease of VEGF, TGFβ, IL6, CXCL1, CXCL9, IL1β, and M2-macrophage-inducing IL4, as well as the increase of immuno-supportive and M1-associated IL12p70 and TNFα." (PMID 34064000, 2021). "In tumor-bearing mice, cDC1 in TME secrete chemokines, such as C-X-C motif chemokine ligand 9 (CXCL9) and CXCL10 to recruit effector T cells to TME." (PMID 34359674, 2021). "The Th1 immune response recruiting NK cells and effector CD8+ T cells was enhanced by CXCL9, CXCL10, and CXCL11 derived from tumor cells, which can limit the diffusion and migration of OvCa cells." (PMID 34248988, 2021). "IL-23+ macrophages expanded anti-tumorigenic Th17 cells that had a distinct phenotype known as Th1-like Th17 cells and promoted tumor-specific immune responses by secreting IFN-γ, CXCL9 and CXCL10." (PMID 33418929, 2021). "We identified multiple tumor-immune interactions, for example between CXCR3, CCL5, TNFRSF1B, and VCAM1-expressing malignant T cells and macrophages/fibroblasts positive for CXCL9, CCR1, GRN, and IGTB1, respectively." (PMID 33816243, 2021). "Using the median value (50–50 division), the expression level of CXCL9, CXCL10, CXCL11, and CCL5 in tumor or adjacent normal tissues allowed the stratification of patients into groups." (PMID 34539647, 2021). "Next, we were struck by the facts that, even at baseline (WT tumors), the concentrations of CXCL9 and CXCL10 in tumor extracts were greater than those of other cytokines by one or two orders of magnitude." (PMID 33664349, 2021). "Many pre-clinical models have shown that eosinophils play a vital role in the tumor microenvironment (TME) and response to immunotherapy through increased expression of CCL5, CXCL9, and CXCL10." (PMID 34732251, 2021). "Accordingly, these effector cells are recruited into tumor tissues by the CXCR3 ligands, CXCL9, CXCL10, and CXCL11." (PMID 34885241, 2021). "Activated eosinophils can secrete chemokines CXCL9, CXCL10, CCL17, and recruit CD4+T and CD8+T cells into the tumour microenvironment." (PMID 35003085, 2021). "Particularly, CXCR3 chemokine receptor, along with ligands CXCL9 and CXCL10, is a major regulator of T cells infiltration to target tumor cells." (PMID 34572592, 2021). "The expression of CXCL9, CXCL10, and CXCL11 except for CCL5 was significantly higher in the tumor compared with the adjacent normal tissues (p = 0.0707, p = 0.0001, p < 0.0001, and p = 0.4207)." (PMID 34539647, 2021). "This is accompanied by decreased expression of CXCL9 and a key transcription factor TCF-1 in the tumor following free CDN2 administration." (PMID 33888863, 2021). "Moreover, as DC-reprogrammed tumor cells could promote the recruitment of T-cells to the tumor site by the secretion of CXCL9 and CXCL10, such strategy could also potentiate the effect of other T-cell-based cancer immunotherapies including immune checkpoint blockade and adoptive cell transfer." (PMID 34367185, 2021). "The importance of CXCR3-ligands in the recruitment of tumor-infiltrating lymphocytes (TILs) to the TME had also been demonstrated in several human cancers in which CXCR3+ TILs were abundant and high levels of CXCL9 and CXCL10 were secreted by stromal cells." (PMID 34944943, 2021). "CXCL9 and CXCL10 are notably context-dependent; they have both an autocrine tumorigenic effect on tumor cells and a paracrine antitumor effect on infiltrating lymphocytes and macrophages depending which cells are expressing its receptor, CXCR342." (PMID 34433873, 2021).
tumor (continued). "Similar studies have shown that increases in CXCL9 and CXCL10 correlate with an enhanced infiltration of T cells, which decreases as tumours become resistant to BRAFi treatment." (PMID 34830780, 2021). "Th1 cells, CD8+ T cells, and NK cells are also the major sources of IFN-γ, which induces the production of CXCL9 and CXCL10 by DCs and other tissue cells in the tumor microenvironment." (PMID 34885241, 2021). "During anti-tumor responses, CD8 effector T cells readily infiltrate B16F10 tumors in a CXCR3-dependent manner in response to CXCL9 and/or CXCL10 expressed by both tumor cells and CD11c+ cells." (PMID 34362825, 2021). "CXCL9 and CXCL11 are known for their tumor suppressive properties and are expressed on the DCs; CXCL9 and CXCL11 have been described to enhance antitumor immunity by activating Th1." (PMID 34484333, 2021). "CXCL9 (p = 0.027), CXCL10 (p < 0.001), CXCL11 (p = 0.002) and CXCL13 (p < 0.001) were significantly up-regulated in tumor tissues compared with tumor-adjacent tissues, while the expression of CXCL12 (p = 0.149) was down-regulated." (PMID 34321012, 2021). "Drugs that augmented paracrine CXCL9/10/11 expression and deactivated CXCR3 expression on tumor cells, have shown anti-tumor activity in several tumor models." (PMID 34321012, 2021). "On the other hand, PBAF inactivation promotes the secretion of chemokines CXCL9 and CXCL10 by tumor cells, which contributes to the increased recruitment of Teff cells to the tumor microenvironment." (PMID 33746989, 2021). "While little is known about CXCL4 expression in GBM, CXCL9, CXCL10 and CXCL11 are expressed by tumor cells." (PMID 34203660, 2021). "IFN-γ-neutralisation abrogated SCC regression, significantly reduced CD8+ T cell-infiltration into SCC, and significantly impaired the secretion of CXCL9, CXCL10 and CCL5 within the tumour microenvironment." (PMID 33925140, 2021). "IFN-γ also enhances blood vessel maturation to promote tumor vascular remodeling and inhibit tumor growth by reducing VEGF-A levels and increasing CXCL9, CXCL10 and CXCL11 levels." (PMID 34294146, 2021). "EZH2-mediated methylation has been demonstrated to repress T helper 1 (Th1) chemokines, CXCL9 and CXCL10, resulting in reduced T-cell recruitment to the tumor microenvironment." (PMID 34140011, 2021). "We found that the protein expression CXCL9 (p = 0.012), CXCL10 (p = 0.003), CXCL11 (p = 0.011), CXCL13 (p = 0.004) were higher in tumor tissues than that in adjacent tissues." (PMID 34321012, 2021). "Inactivation of the machinery down-regulates T cell recruitment chemokines CXCL9 and CXCL10, and remodels a more favorable microenvironment for tumor growth." (PMID 34853298, 2021). "qPCR analysis revealed an increase in the expression of CXCL9 and CXCL10 chemokines from these tumor cells." (PMID 34336705, 2021). "CXCL9/MIG and CXCL10 have been reported to inhibit tumor growth and metastasis of NSCLC and hemangiosarcoma." (PMID 33710817, 2021). "Increased levels of CXCL9 and CXCL10 have been reported to be related to elevated tumor CD8+ T cell density and improved survival in patients with a variety of cancers." (PMID 34249711, 2021). "CXCL9, CXCL10 and CXCL11 are chemoattractant cytokines for anti-tumor leukocytes that express CXCR3, such as effector T cells." (PMID 33446805, 2021). "CXCR3 is the predominant chemokine receptor mediating TE cells recruitment to tumor tissue via its ligands CXCL9 and CXCL10, and has been demonstrated to be crucial for tumor control and survival." (PMID 33466646, 2021). "M1 macrophages produce high levels of CXCL9, CXCL10, and CCL5 that can promote cytotoxic T cell functions with host defense and in tumor." (PMID 34771482, 2021). "For example, chemokines (CXCL9 and CXCR3) can exert antitumor responses by recruiting CD4+ T cells, CD8+ T cells, NK cells and M1 macrophages into the tumor center." (PMID 34335575, 2021).
tumor (continued). "Contributing mechanisms included CD4+ T cell-mediated induction of CXCL9 and CXCL10 in the tumor microenvironment to attract CXCR3-expressing CD8+ T cells or to confer a specific cytotoxic CD8+ T cell effector program amongst others." (PMID 32610710, 2020). "To provide insight into the mechanism resulting in the increased recruitment of cytotoxic T cells into the tumor microenvironment in IKFM mice, we measured expression of CXCL9 in the soluble phase of ascites." (PMID 33028251, 2020). "Other important correlated genes included t CXCL9 and CXCL10, and they served as important regulators of immune activation in tumor microenvironment." (PMID 32231683, 2020). "Neutralization of CD4, CD8, CXCL9, and CXCL10 abrogated the anti-tumor activity of combined therapy." (PMID 33167311, 2020). "Concomitantly, the production of the chemokines CXCL9 and CXCL10 by tumor-localized myeloid cells, including cDC1, was boosted by hetIL-15 in an IFN-γ-dependent manner." (PMID 32461349, 2020). "The CXCL9-11 chemokines are known to bind CXCR3 and are involved in inducing the infiltration of T and NK cells into the tumor as well as tumor suppression." (PMID 32036449, 2020). "The mechanisms by which tumor vessel normalization enhances TIL infiltration are likely to be mediated through chemokines and adhesion molecules, such as CXCL9/10 and ICAM1/E-selectin, respectively." (PMID 32759497, 2020). "Of note, CXCL9 and CXCL10 recruiting pro-tumor immature CD56brightCD16low/neg NK cells are also involved in the recruitment of cytotoxic CD8 T cells." (PMID 33262763, 2020). "The IFN-γ-dependent chemokines CXCL9 and CXCL10 were also assessed in tumor lysates obtained from MC38 bearing-wt and IFN-γ KO mice." (PMID 32461349, 2020). "During hetIL-15 therapy, we observed an upregulation of tumor IFN-γ, both mRNA and protein, together with enhanced expression of the IFN-inducible chemokines CXCL9 and CXCL10." (PMID 32461349, 2020). "High levels of intra-tumoral chemokines such as CCL5, CXCL9, CXCL10 enhance the recruitment of T-cells into the tumor and preclinical studies in mice showed that infiltrating anti-tumor CD8+ T-cells are required for clinical response to anti-PD-1 treatment." (PMID 35582440, 2020). "Therefore, the promotion of STAT‐5 signalling might not only promote CXCR3 expression and the homing of CAR T cells to CXCL9/10‐expressing tumours, but also contribute to the acquisition of CTL activity probably through the induction of T‐bet and thereby CAR T‐cell function." (PMID 31803974, 2020). "CXCL9, CXCL10, and CXCL11 in TME were primarily secreted by tumor cells, monocytes, fibroblasts, and endothelial cells in response to IFN-γ." (PMID 32685487, 2020). "Mechanistically, it has been proposed that EZH2-mediated gene silencing of chemokines, such as CXCL9 and CXCL10, prevents effector T-cell trafficking to the tumor microenvironment, thereby allowing tumor cells to evade immunity." (PMID 33374737, 2020). "For example, leukemia inhibitory factor (LIF) promotes the infiltration of CD163+CD206+ M2 macrophages, and the blockade of LIF in LIF-expressing tumors increases the production of CXCL9, attracting cytotoxic CD8+ T cells to the tumor site." (PMID 32707850, 2020). "There were also increased tumor-infiltrating CD3+/CD8+ T cells in IKFM mice, accompanied by higher levels of CXCL9, a T cell activating factor secreted by macrophages, in IKFM ascitic fluid." (PMID 33028251, 2020). "Individual depletion of CD4 T cells, CD8 T cells and CXCL9, CXCL10, abrogated the anti-tumor activity of combined therapy." (PMID 33167311, 2020). "CXCL9, CXCL10 and CXCL11, chemokine ligands for CXCR3, were expressed at high levels in the tumour locale." (PMID 32439888, 2020). "Previous studies determined the upregulation of genes related to immune cell activation (e.g., CD3D, CD8, CXCR3, CCL5, CXCL9, and CXCL10) in cancer patients with a better prognosis, thereby highlighting the impacts of immune-related genes on tumor progression." (PMID 32775427, 2020).